IL10 (interleukin 10)
Diseases named in the same sentence as IL10 in open-access papers (continued):
Sharing a sentence is not in itself a finding about the gene and the disease.
COVID-19 (continued). "Moreover, exogenous addition of IL-10 significantly downregulated IFN-γ response and several other immune factors in both COVID-19 patients and NO COVID-19-VCs evaluated by ELISA and a multiplex analysis (Luminex) in “study population B”." (PMID 36148228, 2022). "The higher levels of IL-10 among patients with active COVID-19 suggests activated cellular non-specific cellular production by IL-10 producing cells or high ligand action of TLRs." (PMID 36094915, 2022). "However, by an easy to-use whole-blood platform, we showed that the effect of IL-10 was robust on the modulation of specific response to SARS-CoV-2 analyzed on a broad range of immune factors, in both COVID-19 patients and vaccinated individuals." (PMID 36148228, 2022). "Although in our study we identified lower levels of IL-10 in the long COVID-19 group compared to subjects without sequelae in the post-COVID-19 group, IL-17 levels were higher in those subjects with long COVID-19." (PMID 35846757, 2022). "COVID-19 patients show normal level of monocytes with activated phenotype, as evidenced by high FSC (forward side scatter) and potential to secrete cytokines, such as IL-6, IL-10, and TNF." (PMID 35883618, 2022). "In order to further explore the robustness of immune response induced by Janssen COVID-19 vaccine and supplements in BALB/c mice, the present study determined the splenocyte expression of Interleukin-6 (IL-6) and Interleukin-10 (IL-10) cytokines in experimental groups." (PMID 36679902, 2022). "In stage III of COVID-19 patients, moderate positive correlation was noticed between Gal-1 and IL-1β (p = 0.001) and IL6 (p = 0.005) and strong positive correlation between Gal-1 and IL-10 (p = 0.001), IL-23 (p = 0.001) and IL-33 (p = 0.001)." (PMID 35075140, 2022). "In COVID-19, the early stages of disease are characterized by the dramatic rise in concentrations of this cytokine; our work is no different as concentrations of IL-10 were higher in severe COVID-19." (PMID 36430621, 2022). "Similarly, high-level cytokines (e.g., IL-1β, IL-6, IL-8, IL-10, IFN-γ, and TNF-α, etc.)were registered in the blood of Coronavirus Disease 2019 (COVID-19) patients." (PMID 35350754, 2022). "Pregnant women infected with SARS-CoV-2 had increased systemic concentrations of IL-8 (5.9-fold change (FC)), IL-10 (2.3-FC), and IL-15 (1.5-FC) compared to control mothers; such changes were not driven solely by the severe COVID-19 cases." (PMID 35042863, 2022). "Moreover, inflammatory markers such as IL-10 and GRO increased significantly in hospitalized COVID-19 patients, which will result in worse situations if these patients were treated with a high dose of CQ." (PMID 36532753, 2022). "For example, increased expressions of IL10, IL1R2 mRNA and decreased expression of CD74 and CIITA mRNA were described in monocytes of progressive COVID-19 patients compared with stable patients suggesting the acquisition of a regulatory phenotype by myeloid cells." (PMID 36389738, 2022). "In addition, patients with COVID-19 had higher IFN-γ, IL-4, IL-5, and IL-6 concentrations compared to patients with influenza and higher IFN-γ and IL-10 concentrations compared to patients with bacterial CAP." (PMID 34987205, 2022). "In the post-COVID-19 group, subjects with long COVID-19 had higher levels of IL-17 and IL-2 (p<0.05), and subjects without sequelae had higher levels of IL-10, IL-6 and IL- 4 (p<0.05)." (PMID 35846757, 2022). "It is essential for our understanding of the disease course to identify the influence of T-cell subsets and IL-10 in patients with mild and severe COVID-19, as well as in survivor and non-survivor cases." (PMID 35572964, 2022). "The cytokine profile obtained was adequate because it mainly involved anti-viral cytokines IL-12, IL-17A, and IL-2, not cytokines participating in the COVID-19 cytokine storm, such as IL-6 or IL-10." (PMID 35440789, 2022).
COVID-19 (continued). "Comparing surviving vs. nonsurviving COVID-19 patients, after multiple comparison adjustment, IL-10 levels were significantly (adj." (PMID 36414650, 2022). "Finally, COVID-19 worsening during hospitalization is also positively correlated with admission plasma levels of IL-8/CXCL8, MCP-1/CCL2, IL-10, and C-reactive protein." (PMID 36035415, 2022). "Non-inhibition of IL-10 is an advantage, as it is one of the most potent anti-inflammatory cytokines to help fight the COVID-19 cytokine storm." (PMID 36295080, 2022). "TNF-, IL-2, IL-6, IL1B, IL7, IL10, IFN-, GCSF, CXCL10, CCL2, ferritin, D-dimer, fibrinogen, leukocytosis, and C-reactive protein (CRP) levels are significantly higher in critically ill COVID-19 patients." (PMID 35645351, 2022). "For IL-10, we found that serum IL-10 levels were increased in nonsevere and severe cases with COVID-19 compared to healthy subjects (WMD = 1.08, 95% CI: 0.60-1.56, and P < 0.01; WMD = 2.27, 95% CI: 1.26-3.29, and P < 0.01)." (PMID 35540724, 2022). "Moreover, elevated levels of cytokines IL-6, IL-10, and TNF-α were observed in severe COVID-19 patients, directly affecting T-cell subsets and indirectly affecting dendritic cells and neutrophils, thereby reducing lymphocyte count." (PMID 35615369, 2022). "The current observation of the hyper-regulation of IL-10 gene among COVID-19 patients supported the finding that elevated levels of IL-10 in severe COVID-19 patients were initially ascribed to the negative feedback through its anti-inflammatory activities." (PMID 36298704, 2022). "Moreover, in COVID-19 patients, some factors including GCSF, IL10, IL7, IL2, IP10, MCPI, MIP1A and TNFα are elevated in inflammatory response." (PMID 36128671, 2022). "IL-10 is dramatically elevated in COVID-19, and this was believed to be a negative feedback mechanism to suppress inflammation and to induce ARDS, acute-phase protein response, severe pneumonia, and damage to vital organs." (PMID 35464491, 2022). "In addition, Tim-3+ NKT cells in COVID-19 presented a stronger capacity to secrete IFN-γ, IL-4 and IL-10 compared with healthy individuals, they also demonstrated high expression of co-inhibitory receptors such as PD-1, CTLA-4, and LAG-3." (PMID 35250975, 2022). "Non-pregnant patients with severe COVID-19 have been found to have greater levels of IL-2, IL-6, IL-7, IL-10, IP-10, MCP-1, TNF-α, macrophage inflammatory protein 1 alpha, and granulocyte-CSF than those with mild and moderate infections." (PMID 36383608, 2022). "The cytokine storm has already been attenuated following recovery from COVID-19, as levels of TNF-α, free active TGF-β, IFN-γ, IL-1β, IL-2, IL-4, IL-6, IL-8, IL-10, IL-12p70, IL-17 and MCP-1/CCL2 during convalescence were not higher compared to healthy volunteers." (PMID 35757700, 2022). "Higher levels of IL-2, IL-10, IFN-γ, and MCP-1 are indicators of mild COVID-19." (PMID 36561720, 2022). "In Non-SOT COVID-19 patients, we observed 6 (IL-13, IL-10, IFN-γ, IL-12p70, MCP-2, IL-6) and 9 (IL-16, IL-13, TNF-α, IL-6, IL-18, IL-15, MIP-1α, IL-2Ra, IL-8) cytokine correlations with monocyte and neutrophil derived cfDNA, respectively." (PMID 35075453, 2022). "Indeed, serum levels of inflammatory mediators and markers, including interleukin (IL)-6, C-reactive protein (CRP), IL-1β, IL-10, CXCL9, CXCL10, ferritin, and tumor necrosis factor-α (TNF-α) are elevated in cases of COVID-19." (PMID 35053424, 2022). "In relation to individuals in the post-COVID-19 group, higher levels of IL-10 and IL-4 were observed in the group that did not present sequelae after the disease." (PMID 35846757, 2022). "Therefore, we analyzed the viral loads and the differential gene expression profiles of eight cytokines (IL-1, IL-2, IL-4, IL-6, IL-10 IFN-γ, TNF-α, and TGF-β1) in a total of 118 qPCR confirmed COVID-19 cases." (PMID 36584119, 2022).
COVID-19 (continued). "Furthermore, IL-33 induces IL-10 production and enhanced IL-10 has been correlated with increasing IFN-γ producing CD4+/CD8+T cells and PD1+/Tim3+ population – ensuing in T cell exhaustion in severe COVID-19 patients." (PMID 35431536, 2022). "Significantly elevated levels of inflammatory cytokines TNF-α, IL-1, IL-6, and IL-10 have been documented in cases of severe COVID-19 compared to cases of non-severe disease." (PMID 36282812, 2022). "The increased production of IL-10, but not of IL-4, in severe COVID-19 suggests that IL-10 is the main cytokine that counteracts the inflammatory response cascade triggered by the Th1 type response." (PMID 36287506, 2022). "When cytokine levels were evaluated in the culture media of PBMCs derived from healthy individuals and COVID-19 patients, a higher tendency to secrete cytokines such as IL-1b, TNF, IL-6, INFg, IL-17, MCP-1, and IL-10 was observed in cells exposed to SARS-COV2 infection." (PMID 35831294, 2022). "Moreover, the statistical analysis highlighted the increased level of IL-10 and Gal-1, as well as a strong positive correlation between them in stage III of COVID-19, suggesting their dependent immunomodulation." (PMID 35897786, 2022). "Lower IL-12p70/IL-10 and IFN-γ/IL-10 ratios were found in the control group without SIgA than the control group with SIgA and the COVID-19 group with SIgA." (PMID 35686128, 2022). "Elevated levels of IL-6, IL-10, and TNF-α in COVID-19 patients promote the expression of PD-1 and T-cell immunoglobulin mucin 3 (Tim-3) on the surface of peripheral T cells that act as exhaustion signals, resulting in decreased T-cell function and memory T-cell activity." (PMID 35615369, 2022). "Interestingly, obviously elevated IL-2, IL-8, IL-10, TNF-α, and IL-12p70 were observed in symptomatic patients with COVID-19 compared with asymptomatic carriers, which were consistent with the results in that of patients with COVID-19." (PMID 35685940, 2022). "A previous study suggested a reduction in T cell counts in COVID-19 patients and high levels of pro-inflammatory markers such as TNF-α, IL-6, IL-8, and IL-10 may be a potential reason for the killing of T cells." (PMID 35890093, 2022). "Elevated levels of cytokines such as IL1B, IL7, IL8, IL9, and IL10, monocyte chemoattractant protein and tumor necrosis factor (TNF), among others, in COVID-19 have been reported and elevated proinflammatory cytokine levels have been found to correlate with disease severity." (PMID 35172279, 2022). "Added to combining selective recognized biochemical markers of COVID-19 severity (ANC, CRP, LDH, BUN and ferritin), the triad of elevated serum IL-10, PD-L1 and TNF-α improved the current model accuracy to predict the severity of the disease, through the stepwise linear regression model." (PMID 35529862, 2022). "Network analysis of inflammatory mediators in the nasal mucosa and serum showed an anti-inflammatory response (IL-10 upregulation) and T2 inflammatory (CCL11 and CCL24 upregulation) response with co-existent inflammation (upregulation of IL-6 and CXCL8) in early COVID-19." (PMID 35397798, 2022). "Our results showed that serum IL-2, IL-4, IL-6, and IL-10 levels were elevated in COVID-19 patients compared to healthy controls, and IL-6, IL-8, and IL-10 levels were increased in severe COVID-19 cases compared to nonsevere patients." (PMID 35540724, 2022). "The surviving severe COVID-19 patients showed significantly lower circulating concentrations of TNFα, TGFα, IL-10, sRAGE, sTNF-RI and sTNF-RII compared to the non-survivors (p = 0.001, p = 0.031, p < 0.0001, p < 0.0001, p = 0.001 and p < 0.0001, respectively)." (PMID 36142255, 2022). "The aim of this study was to determine the association of Gal-1 and innate immunity cytokines such as IL-1β, IL-6, IL-10, IL-23, IL-33 with disease severity, alongside with clinical, biochemical features and Chest X-rays (CXR) lung findings in 210 patients with COVID-19." (PMID 35075140, 2022).
COVID-19 (continued). "Indeed, elevated levels of various interleukins such asIL-6, IL-1β, TNF-α, IL-10, and IL-8 and the chemokine MCP1 have been well documented in patients with severe COVID-19." (PMID 36016187, 2022). "In our study, the cytokines IL-6, IL-10, and TNF-α were significantly upregulated in severe COVID-19 patients, especially in male patients, indicating that IL-6 antagonists and TNF-α inhibitors are more appropriate used in male patients to reduce both severity and mortality rate of COVID-19." (PMID 35237162, 2022). "Compared to those with non-severe COVID-19, patients with severe COVID-19 had significantly higher circulating levels of neutrophil-to-lymphocyte ratio, C-reactive protein, procalcitonin, D-dimer, IL-6 and IL-10 both in MAFLD and in non-MAFLD patients." (PMID 33763027, 2021). "Another study showed that Shufeng Jiedu prescription may prevent COVID-19 through its active ingredients likely quercetin, luteolin, wogonin, and kaempferol by targeting TNF, IL-10, IL-2, IL-6, STAT1, and CCL-2." (PMID 34861881, 2021). "Most of the included studies also showed a significant elevation of circulating IL-10 in severe COVID-19 patients compared to non-severe groups." (PMID 34046036, 2021). "Interleukin 10 is considered to be a negative modulator of inflammation; however, in COVID-19 patients, it seems to play a relevant pro-inflammatory role." (PMID 34572581, 2021). "The plasma from severe COVID-19 patients similarly exhibited increased IL-6, IL-10, and MCP-1 levels, but these levels were not as high as those in patients with CRS from other causes such as sepsis and burns." (PMID 34867988, 2021). "A study conducted in ICU and non-ICU COVID-19 patients in Wuhan, China, reported elevated levels of IL-1β, IL-7, IL-8, IL-9, IL-10, FGF, G-CSF, GM-CSF, IFN-γ, IP-10, MCP-1, MIP-1α, MIP-1β, PDGF, TNF-α and VEGF in patients compared to healthy controls." (PMID 34603318, 2021). "In COVID-19 patients, the cytokine storm was mediated by high-levels of proinflammatory cytokines, and the severe cases showed significantly higher cytokines and chemokines, such as TNF-α, IL-6, and IL-10 expressed." (PMID 34439967, 2021). "Moreover, cytokines such as IL-6, IL-10, and TNF-α were revealed to increase with the severity of the diseases in COVID-19 patients." (PMID 33557779, 2021). "Additionally, the anti-inflammatory activity, promoted by MSCs in COVID-19 patients, it was demonstrated by a decreased level of TNF-α, and a concurrent elevation in the concentration of the IL-10." (PMID 33815867, 2021). "IL-10 blockades revealed a capacity of enhancing pathogen clearance in previous mouse model, however, their application in clinical settings for COVID-19 patients has not been reported." (PMID 34088317, 2021). "We have observed that the proportion of diabetes in patients with mild and severe cases with COVID-19 (MS and SCS group) was higher than that of AS group, and the concentration of IL6, IL8 and IL10 in MS and SCS groups was higher than that of AS group (P < 0.05)." (PMID 34118952, 2021). "Considering the objectives of our study, we highlight that there were significant, direct correlations between CCl2, galectin-3, PON1 concentration, CRP, IL-10, IL-6, and angiotensin II in COVID-19 positive patients, but not in the COVID negative ones." (PMID 34205807, 2021). "In fact, patients with COVID-19 display a pro-inflammatory (IL-1β, IL-6, IL-7, IL-8, IL-9, FGF, G-CSF, GM-CSF, IFN-ɣ, CXCL10, CCL2, CCL3, CCL4, PDGF, TNFα, and VEGF) and regulatory cytokine profile (IL-10 and TGFβ; cytokine storm)." (PMID 33995342, 2021). "However, in relation to the group mild B COVID-19 subgroup, it is possible to highlight other significant positive correlations between IL-37 and the cytokines IFN-α, IFN-γ, IL-6, and IL-10." (PMID 33717074, 2021).
COVID-19 (continued). "Higher blood levels of inflammatory biomarkers (e.g. CRP) and cytokines (e.g. IL2, IL7, IL10, etc.)have been reported in COVID-19 patients admitted to the ICU3, and IL6 and IL10 have been determined to be strong discriminators for severe disease and death, consistent with our findings." (PMID 33627696, 2021). "For instance, patient DRASTIC-063 displayed higher IFN-2, IL-10, IL-12p70 and IL-17A in ETA (d8) than other COVID-19 respiratory samples, while the plasma (d7) level of IFN-2 was also higher, DRASTIC-063 had higher plasma level of IL-18 but not IL-10, IL-12p70 or IL-17A." (PMID 34462740, 2021). "PIMS-TS children had significantly elevated levels of cytokines, IFNγ, IL-2, TNFα, IL-1α, IFNα, IFNβ, IL-6, IL-15, IL-17A, GM-CSF, IL-10, IL-33 and IL-Ra; elevated chemokines, CCL2, CCL19, CCL20 and CXCL10 and elevated VEGF, Granzyme B and PDL-1 in comparison to COVID-19, seropositive and controls." (PMID 33813138, 2021). "However, it was observed that severe COVID-19 patients also display increased levels of TGF-β and IL-10 in their sera, suggesting the activation of immunoregulatory cytokines as well." (PMID 33692788, 2021). "As a remarkable difference though, blood levels of IL-10 are consistently elevated in active COVID-19 but remained unchanged in SARS, where levels did not rise until convalescence." (PMID 33746948, 2021). "In a subgroup of 49 available plasma samples from COVID-19 patients, collected at a median of 2.8 (2.1–3.7) months after baseline, circulating levels of PAMPs (16S rDNA), DAMPs (mtDNA), and cytokines (IL-6, TNF-α, and IL-10) were quantified." (PMID 34659235, 2021). "However, its decrease in COVID-19 patients significantly increases the secretion of pro-inflammatory factors such as IL-6, TNF-α, MCP-1, and IL-1 β, and decreases the secretion of IL-10 and transforming growth factor-β (TGF-β)." (PMID 35062245, 2021). "We found significant direct correlations between galectin-3, CCL2, PON1, IL-6, IL-10, CRP, ACE2, and angiotensin II concentrations in COVID-19 positive patients as well as with aminotransferase activities and triglycerides, and inverse correlations with HDL-cholesterol." (PMID 34205807, 2021). "The present study aimed to investigate whether serum levels of NLRP3, HMGB1, IL-6, IL-10, angiotensin II and ACE2 were different in COVID-19 patients with headache." (PMID 34384355, 2021). "Our meta-analysis revealed significantly lower levels of immune cells (CD3+ T, CD4+ T, CD8+ T, B and NK cells), higher levels of cytokines (TNF-α, IL-5, IL-6 and IL-10) and higher levels of chemokines (MCP-1, IP-10 and eotaxin) in severe cases in comparison to mild cases of COVID-19." (PMID 34344353, 2021). "Unlike in SARS and MERS patients, high levels of IL-10 have been demonstrated in severe and critically ill COVID-19 patients." (PMID 34046036, 2021). "Currently, multiple biomarkers in COVID-19 have been identified, such as leukocytes, C-reactive protein (CRP), procalcitonin (PCT), lactate dehydrogenase (LDH), ferritin, and cytokines (IL-2R, IL-6, IL-8, IL-10, and TNF-α)." (PMID 34573984, 2021). "There is emerging evidence of cytokine over-production, in particular IL-6 and IL-10, as part of immunopathogenesis within COVID-19; however, drivers of these observed changes are still not fully understood." (PMID 33493185, 2021). "Based on ROC analysis, nine biomarkers (TNF-α, IL-10, MIG, IL-6, IP-10, M-CSF, G-CSF, GM-CSF, IFN-α2) were established as good early predictors for COVID-19 patients who may require ICU admission." (PMID 34858428, 2021). "IL-6 (proinflammatory) and IL-10 (anti-inflammatory) are two cytokines commonly dysregulated in COVID-19 patients and the ratio of IL6-to-IL10 may be used to predict outcomes of COVID-19 patients." (PMID 33780352, 2021). "The concentration level of IL-10 was measured in eleven studies, of which seven studies reported a significant difference between severe COVID-19 patients compared to non-severe groups." (PMID 34046036, 2021).